RNU6-1044P (RNA, U6 small nuclear 1044, pseudogene)
Gene: Small nuclear RNA gene on chromosome X (73,397,531 to 73,397,637, reverse strand). Ensembl gene ENSG00000207486.
Homologues: Orthologues: chimpanzee U6 (99% identical). Paralogues in human: RNU6-1243P (83% identical), RNU6-1060P (82% identical), RNU6-141P (82% identical), RNU6-242P (82% identical), RNU6-379P (82% identical), RNU6-43P (82% identical), RNU6-455P (82% identical), RNU6-543P (82% identical), RNU6-1019P (81% identical), RNU6-1122P (81% identical), RNU6-1151P (81% identical), RNU6-1152P (81% identical), and 1284 more.